FAM120C (family with sequence similarity 120 member C)
Synonyms: CXorf17; ORF34; FLJ20506
Tractability: PROTAC: UniProt records ubiquitination sites on it; ubiquitination databases record sites on it; its protein half-life has been measured.
Gene: Protein-coding gene on chromosome X (54,068,324 to 54,183,281, reverse strand). Ensembl gene ENSG00000184083.
Subcellular location (Human Protein Atlas): Nuclear membrane; Endoplasmic reticulum
Gene Ontology:
Molecular function: RNA binding
Cellular component: nucleus
Homologues: Orthologues: chimpanzee FAM120C (99% identical), macaque FAM120C (99% identical), rabbit FAM120C (95% identical), mouse Fam120c (92% identical), rat Fam120c (92% identical), pig FAM120C (82% identical), dog FAM120C (81% identical), tropical clawed frog fam120c (70% identical), guinea pig FAM120C (64% identical), zebrafish fam120c (60% identical). Paralogues in human: FAM120A (56% identical), FAM120B (17% identical).
Diseases named in the same sentence as FAM120C in open-access papers:
FAM120C is named in the same sentence as 10 diseases in open-access papers, as found by Europe PMC text mining. Sharing a sentence is not in itself a finding about the gene and the disease. The quoted sentences say what the papers report.
autism (3 papers, 2015 to 2018). Persistent deficits in social interaction and communication and interaction as well as a markedly restricted repertoire of activity and interest as well as repetitive patterns of behavior. "FAM120C encodes a potential transmembrane protein and lies in a region where mutations and deletions have been associated with intellectual disability and autism." (PMID 30598092, 2018).
osteosarcoma (1 paper, 2023). A usually aggressive malignant bone-forming mesenchymal neoplasm, predominantly affecting adolescents and young adults. "These RBPs include NOP58, FAM120C, DYNC1H1, TRAP1, and LMNA, which may serve as molecular targets for osteosarcoma immune regulation." (PMID 37139238, 2023).
triple-negative breast carcinoma (1 paper, 2024). An invasive breast carcinoma which is negative for expression of estrogen receptor (ER), progesterone receptor (PR), and human epidermal growth factor receptor 2 (HER2). "Notably, the TRs of several genes, including SYNGR1, GTF2IRD2, and FAM120C, exhibited increased levels in the tumor samples of triple-negative breast cancer patients, whereas genes such as TVP23C, ICAM3, and RIMKLB displayed decreased TRs in triple-negative breast cancer tumor samples." (PMID 39349823, 2024).
FAM120C also shares sentences with these, for which no sentence is quoted: infection (6 papers); Intellectual disability (2); abortion (1); Arthritis (1); developmental delay (1); tumor (1); viral infection (1).